TNF (tumor necrosis factor)
Diseases named in the same sentence as TNF in open-access papers (continued):
Sharing a sentence is not in itself a finding about the gene and the disease.
candidiasis (continued). "C. albicans infection is associated with increased levels of pro inflammatory monocyte derived cytokines such as TNFα, IL-1, and IL-6 as well as high IL-10, which contribute to the suppression of immunity against candidiasis." (PMID 23144764, 2012). "Of the cytokines induced, IL-1α, IL-1β, IL-6, IL-10, IL-17A, IL-18, IFN-γ, and TNF-α have been previously shown to play an important role in the pathogenesis of invasive candidiasis in vivo." (PMID 22916017, 2012). "A dramatic augmentation of TNF-α was verified in elderly D.S., indicating an exacerbated proinflammatory response against Candida infection." (PMID 19327169, 2009). "Furthermore, EVs administered to mice before inducing candidiasis influenced higher levels of TNF-α, IL-4, IL-10, IL-12p70, TGF-β and IFN-γ." (PMID 39877654, 2024). "Consumption of corticosteroids, antibiotics, and TNF-α inhibitors, as well as undergoing mechanical ventilation, central venous catheterization, and extracorporeal membrane oxygenation (ECMO) are risk factors for developing candidiasis." (PMID 35816494, 2022). "Previous studies have already shown the protective effect of TNF-α during candidiasis." (PMID 35898912, 2022). "However, WT and Gsdmd-/- macrophages generated the same amount of TNFα and IL-6 after Candida infection, supporting the notion that the expression and secretion of these cytokines were GSDMD-independent." (PMID 34795266, 2021). "Candida infection also directly triggered TNFα and IL-6 production in macrophages." (PMID 34795266, 2021). "Similarly, this mutant elicited a poor serum pro-inflammatory cytokine response as judged by IFNγ and TNFα levels and showed reduced virulence in a mouse model of systemic candidiasis." (PMID 22114559, 2011). "Mouse model studies have shown that AMPs can control candidiasis, such as Gomesin, a cationic peptide of 18 amino acids obtained from the caranguejeira spider from Brazil, which protected C. albicans-infected mice and induced pro-inflammatory cytokines such as TNF-α, IFN-ɣ, and IL-6." (PMID 40985427, 2025). "Children with candidiasis showed significantly elevated salivary concentrations of IL-1β (34.5 ± 9.1 vs. 15.2 ± 5.8 pg/mL; p < 0.001), IL-6 (28.9 ± 8.3 vs. 12.4 ± 4.9 pg/mL; p < 0.001), TNF-α (36.8 ± 10.2 vs. 18.7 ± 6.2 pg/mL; p < 0.001), and IL-8 (41.5 ± 11.5 vs. 22.1 ± 7.3 pg/mL; p < 0.001)." (PMID 41301927, 2025). "Traditionally, candidiasis has not been linked to TNFα inhibition, but new data suggest that TNFα inhibitors may in fact increase the risk of OPC." (PMID 24513269, 2014). "Somewhat surprisingly, Candida infections are not widely reported in RA; however, recent epidemiologic data from patients with inflammatory bowel disease demonstrate that TNFα inhibitors increase the risk of oropharyngeal candidiasis (OPC) at rates similar to mycobacterial infections." (PMID 24513269, 2014). "TNFα Blockade Therapy has been associated with invasive fungal infections, including histoplasmosis, candidiasis, and aspergillosis, with a review from 2008 identifying 64 reported cases of IPA in patients receiving TNFα blockers, with an overall mortality rate of 82%." (PMID 40863508, 2025). "In Onygenales, this was the only deficient cytokine reported, while, in contrast, in seven cases of Candida infection GM-CSF or TNFα were absent instead." (PMID 32849462, 2020). "Probably, the higher level of TNF-α and CXCL8 detected in the saliva from elderly D.S. helps to avoid a more invasive C. albicans infection since these cytokines/chemokines play an important role in the innate resistance to oral and systemic Candida infections." (PMID 19327169, 2009).
enthesitis (49 papers, 2009 to 2025). Inflammation at the site of insertion of ligaments, tendons, and other fibrous structures into bone. "TNF-α levels showed an association with inflammatory markers and were higher in patients with peripheral enthesitis." (PMID 40807227, 2025). "These disorders are associated with enthesitis, which is the cardinal SpA lesion, and associated with both tumor necrosis factor (TNF) and interleukin‐23 (IL‐23)/IL‐17 pathway dysregulation at the synovio‐entheseal complex leading to joint inflammation." (PMID 40320905, 2025). "Disease initiated with inflammation at the periphery of the intervertebral disc (IVD) adjacent to the longitudinal ligament, reminiscent of enthesitis, and was associated with upregulated tumor necrosis factor and metalloproteinases." (PMID 26831337, 2016). "These proinflammatory cytokines drive enthesitis onset and progression, making the IL-23/IL-17 axis and TNF-α key therapeutic targets." (PMID 40677616, 2025). "To mimic acute and chronic enthesitis, we exposed the cells in the fibrocartilaginous compartment to a combination of IL‐17, IL‐23 and TNF‐α for 3 or 21 days, respectively." (PMID 39188199, 2024). "We have successfully developed an enthesis‐on‐chip model from hMSCs, which is capable of emulating some of the key features of acute and chronic enthesitis, after the treatment with IL‐17, IL‐23 and TNF‐α." (PMID 39188199, 2024). "The anti-TNF agents used by patients with resolved enthesitis were etanercept (7 patients), infliximab (3 patients), and adalimumab (1 patient)." (PMID 36639793, 2023). "Concerning patients with unresolved enthesitis, 4 were receiving anti-TNF therapy (2 with etanercept and 2 with adalimumab), one was on sulfasalazine monotherapy, and 10 were without any treatment." (PMID 36639793, 2023). "After 2 years of follow-up, patients with persistent enthesitis were less frequently under anti-TNF therapy (4/15, 26.7%) than patients with resolved Achilles enthesitis (11/31, 35.5%), without significant differences." (PMID 36639793, 2023). "It would not be unexpected if a similar defect in human BM-MSCs contributed to the development of enthesitis in response to TNF stimulation." (PMID 35892597, 2022). "The diagnosis time of ≤ 3 months, AJC > 4, with enthesitis, high TNF-a levels and JSpADA scores were potential predictors of ERA (P < 0.1)." (PMID 36461063, 2022). "The human TNF transgenic (hTNFtg) and the TNFΔARE mice lack typical SpA features like spondylitis and enthesitis but instead develop destructive polysynovitis reminiscent of RA." (PMID 34095174, 2021). "In contrast, tumor necrosis factor inhibitors (TNFi’s) have been shown to be effective in improving or resolving enthesitis in clinical trials in patients with axSpA." (PMID 34107999, 2021). "In the B10Q.Ncf1m1j/m1j model, mice developed enthesitis and dactylitis three days after an intra-peritoneal injection of mannan; the disease drivers were tumor necrosis factor (TNF)-producing myeloid cells and IL-17A-producing γδ T cells." (PMID 34204773, 2021). "The advent of TNF inhibitors has promised to be a “game changer,” given their relatively high efficacy for enthesitis and axial disease." (PMID 34124112, 2021). "Another possible solution is to treat children diagnosed with JoSpA more aggressively early on, incorporating TNF inhibition for their peripheral arthritis and enthesitis prior to the development of axial disease." (PMID 34124112, 2021). "Recently, biologics such as TNF-α inhibitors have been reported to be effective for skeletal AS manifestations such as spinal and sacroiliac pain, peripheral arthritis, and enthesitis." (PMID 33021982, 2020). "TNF blockade is the standard of care for enthesitis and severe axial disease in those patients with partial response to conventional DMARDs." (PMID 29846815, 2018). "Other mouse models of soluble (TNFΔARE) or membrane bound TNF-α overexpression also result in enthesitis and spinal arthritis/ankylosis phenotypes." (PMID 28791018, 2017).
enthesitis (continued). "Different aspects of the disease activity, such as dactylitis and enthesitis, were effectively controlled by anti-TNF therapy, and also by ustekinumab and secukinumab." (PMID 26892034, 2016). "Generally, the grades of dactylitis and enthesitis in PsA patients have been suggested to be partly influenced, that is, enhanced, by TNF-α, which is supported by the efficacy of TNF-α blockers in PsA therapy." (PMID 24321127, 2013). "This patient has severe enthesitis and mild skin disease, and he has failed therapies for mild and moderate enthesitis; a TNF inhibitor should be considered." (PMID 18952643, 2009). "This study aimed to evaluate the efficacy of molecular-targeted therapies in patients with PsA presenting with enthesitis in comparison with placebo or TNF-α inhibitors (TNFis), especially adalimumab, and identify the latest evidence on their efficacy for PsA-related enthesitis." (PMID 40677616, 2025). "Additionally, CD4+ and CD8+ T cells at entheses produce IL-17 and TNF-α, contributing to enthesitis." (PMID 40677616, 2025). "However, TNF-α levels were significantly elevated in patients with peripheral involvement, particularly those presenting with enthesitis (p = 0.036)." (PMID 40807227, 2025). "The demographic, clinical, and biological variables measured were age, time since PsA diagnosis, smoking, type of treatment used, clinical form, presence of enthesitis, dactylitis (present or past), fatigue, tumor necrosis factor (TNF)-alpha, and interleukin 6 (IL-6)." (PMID 38978782, 2024). "As for the use of IL-12/IL-23 inhibitors in the treatment of PsA, a prospective randomized-controlled open-label study concluded that they could outperform TNF inhibitor treatment in terms of enthesitis remission rate." (PMID 36811818, 2023). "In addition, the mean global VAS, BASDAI, and ASDAS-CRP scores were significantly higher among patients with Achilles enthesitis over the 2 years of follow-up after adjusting for age, BMI, and current anti-TNF intake." (PMID 36639793, 2023). "The low frequency of anti-TNF treatment in patients with persistent enthesitis might be related to these findings." (PMID 36639793, 2023). "IL-17 is pro-inflammatory and can synergize with TNF to orchestrate synovitis and enthesitis." (PMID 34095174, 2021). "The data supporting these contentions, mostly obtained from adult studies, has led to revisions in current ACR treatment guidelines supporting earlier use of biologic DMARDs (e.g., TNF inhibitors) following NSAID failure in children with sacroiliitis or enthesitis." (PMID 34124112, 2021). "TNF inhibitors markedly reduce symptoms such as back pain and enthesitis; however, it is still unclear whether these new treatments lead to a reduction in bone complications." (PMID 24935156, 2014). "Tumor necrosis factor (TNFα) blockers have been verified to be useful in the management of many clinical disease expressions of PsA including peripheral arthropathy, axial involvement, enthesitis, and cutaneous manifestations." (PMID 22649467, 2012). "Similarly, other randomized controlled trials (RCTs) of TNF antagonists have not consistently demonstrated significant improvements in both enthesitis and peripheral arthritis for TNF-antagonist-treated patients compared with placebo-treated patients." (PMID 20230622, 2010). "In addition to blood samples, other studies explored various predictors to forecast treatment efficiency, revealing factors like secukinumab dosage, prior anti-tumor necrosis factor (TNF) treatment, methotrexate usage, baseline enthesitis, PsA disease duration, and PASI score." (PMID 38672786, 2024). "In summary, etanercept has proven efficacy in skin and joint disease as well as nail disease, dactylitis and enthesitis, and may relieve symptoms of fatigue and depression, although, as detailed above, it appears as it is less effective than other anti-TNF drugs." (PMID 26892034, 2016).
enthesitis (continued). "Many observational and randomized clinical trials (RCTs) have evaluated the effect of IL-17, IL-23, TNF, and JAK inhibition on the resolution of enthesitis." (PMID 36639793, 2023). "TNF plays a key role in the pathogenesis of IBD, in which enthesitis is also a typical manifestation when the disease also involves extra-intestinal structures." (PMID 29846815, 2018). "In a TNF transgenic mouse model, the selective expression of TNF receptor I in mesenchymal cells was detected, and enthesitis occurred regardless of the presence or absence of mature T and B cells." (PMID 35892597, 2022). "In the DBA/1 mouse model of ankylosing enthesitis, TNF blockade with the soluble TNF receptor etanercept did not inhibit the formation of new cartilage and bone at the enthesis." (PMID 34095174, 2021). "Median changes in swollen-joint count and in enthesitis score were similar in patients with and without prior TNF-antagonist treatment." (PMID 20553600, 2010). "Pre-clinical studies suggest a fundamental role for JAK signalling in the pathogenesis of enthesitis, and upadacitinib has been shown to inhibit the phosphorylation of the signalling molecule STAT1 in entheseal cells, leading to reduced production of the inflammatory cytokines TNF and IL-17." (PMID 38331400, 2024). "When comparing HLA-B27+ enthesitis-related JIA with other juvenile arthritis groups (i.e., psoriatic, oligoarticular, polyarticular, undifferentiated, and Lyme arthritis), cytokine receptor interaction, JAK-STAT, IL-17, and TNF signalling pathways were enriched." (PMID 37848930, 2023). "In addition, T cells are not essential for the development of enthesitis in TNFΔARE mice (deleting TNF AU-rich elements (ARE) from the mouse genome on the regulation of TNF biosynthesis) and entheseal ossification in an aged DBA/1 mouse." (PMID 35222393, 2022). "Notably, adalimumab therapy reduced peripheral arthritis and enthesitis; the effectiveness of adalimumab for these extraaxial manifestations was very similar for patients with and without prior TNF-antagonist treatment." (PMID 20553600, 2010). "However, little is known on the median time to resolve enthesitis, and the magnitude of response by enthesitis severity, by time since diagnosis, or after switch to other TNF inhibitors as well as development of enthesitis over time in patients with no enthesitis at baseline." (PMID 31801620, 2019). "However, the improvements in enthesitis with tofacitinib vs placebo in a study of patients with inadequate response to TNF inhibitors failed to achieve statistical significance, potentially suggesting that different JAK inhibitors may affect enthesitis to different extents." (PMID 38331400, 2024). "At week 12 of the study, patients with AS with peripheral arthritis or with enthesitis at baseline and previous treatment with TNF antagonists experienced quite similar improvements in joint counts and in MASES, as did patients without a history of anti-TNF therapy." (PMID 20553600, 2010).
Epstein-Barr virus infection (49 papers, 2012 to 2025). An infection that is caused by Epstein-Barr virus. "KEGG analysis highlighted that MMRG genes were most associated with Epstein-Barr virus infection, the TNF signaling pathway, the NOD-like receptor signaling pathway, and influenza A." (PMID 40153427, 2025). "Combination treatment with CV8102 and anti-PD-1 antibodies increased the upregulation of these gene sets and induced additional gene sets associated with TNF signaling, cytosolic-DNA-sensing and Epstein-Barr virus infection, indicating a synergistic effect of anti-PD-1 treatment with CV8102." (PMID 36319717, 2023). "We then carried out a KEGG/GSEA functional enrichment analysis of DEGs between M1 and M0, enriching significant biological functions including Epstein-Barr virus infection, Kaposi sarcoma-associated herpesvirus infection, Ribosome, TNF signaling pathway, and Proteasome." (PMID 37288756, 2023). "These pathways included the NOD-like receptor signaling pathway, cytokine-cytokine receptor interaction, hematopoietic cell lineage, TNF signaling pathway, Th17 cell differentiation, and Epstein-Barr virus infection." (PMID 40153427, 2025). "Concurrently, KEGG enrichment analysis showed that the differentially expressed genes were primarily involved in the TNF signaling pathway, IL-17 signaling pathway, human cytomegalovirus infection, Epstein-Barr virus infection, and cancer-related pathways." (PMID 40182927, 2025). "The KEGG pathway enrichment analysis revealed that these genes were primarily enriched in Epstein-Barr virus infection, TNF signaling pathway, and cytokine-cytokine receptor interaction." (PMID 39840076, 2024). "Functional enrichment analysis indicated that these genes were mainly concentrated in “Epstein-Barr virus infection”, “TNF signaling pathway”, and “Cytokine-cytokine receptor interaction” in KEGG pathways." (PMID 39840076, 2024). "We found that the top 5 enriched pathways for downregulated DEGs were cell cycle, DNA replication, Epstein-Barr virus infection, mismatch repair and TNF signaling pathway." (PMID 37464398, 2023). "Such as TNF signaling pathway, Epstein-Barr virus infection, MAPK signaling pathway, Pathways in cancer." (PMID 31138194, 2019). "BCG-treated patients and one placebo-treated patient who, after enrollment, unexpectedly developed acute Epstein-Barr virus infection, a known TNF inducer, exclusively showed increases in dead insulin-autoreactive T cells and induction of Tregs." (PMID 22905105, 2012). "The TNF-induced death in vivo of insulin-autoreactive T cells with BCG vaccinations or acute EBV infection was confined to the autoreactive T cells." (PMID 22905105, 2012). "Functional enrichment analysis of all genes in the PPI network showed that they were enriched in the following immune-related pathways: “T cell receptor signaling pathway”, “Natural killer cell mediated cytotoxicity”, “Epstein-Barr virus infection”, and “TNF signaling pathway”." (PMID 33403044, 2021). "EBV infections, like BCG, trigger innate immunity by inducing secretion of host TNF." (PMID 22905105, 2012). "In addition, these genes were both significantly associated with 6 KEGG pathways, including “HIF-1 signaling pathway”, “MicroRNAs in cancer”, “Pathways in cancer”, “Epstein-Barr virus infection”, “NOD-like receptor signaling pathway” and “TNF signaling pathway”." (PMID 35495160, 2022). "In addition, GO analysis indicated that 1476 DEGs mainly engaged in the inflammatory response and regulation of cytokine production, while the main enriched KEGG pathways were EBV infection, NOD-like receptor signaling pathway, NF-κB signaling pathway, and TNF signaling pathway." (PMID 34938813, 2021). "For example, Epstein-Barr virus infection in B or T cells induced TNF-α, but not IL-1α." (PMID 33072000, 2020).